WDR72 (WD repeat domain 72)
Diseases named in the same sentence as WDR72 in open-access papers (continued):
Sharing a sentence is not in itself a finding about the gene and the disease.
liver fibrosis (1 paper, 2024). "Based on existing knowledge, this research represents the primary exploration of the role of WDR72 in liver fibrosis." (PMID 38287425, 2024). "The mechanism of CBS, CYP1A2, FOXA1, GSTZ1, WDR72 and UHMK1 in the progression of liver fibrosis is still unclear." (PMID 38287425, 2024). "According to the validation of clinical specimens, CBS, CYP1A2, FOXA1, GSTZ1, WDR72 and UHMK1 were specifically expressed in patients with liver fibrosis or hepatocirrhosis." (PMID 38287425, 2024).
renal clear cell carcinoma (1 paper, 2022). "However, recent studies have found that the ENAM gene is associated with T classification and inhibits the proliferation of renal clear cell carcinoma and that WDR72 genomic variants are associated with distal tubular acidosis and rapid declines in renal function." (PMID 35875087, 2022).
tumor (11 papers, 2017 to 2026). "Meanwhile, regulatory T (Treg) cells, which can promote tumor evasion of immune surveillance and are considered as the chief obstacle to antitumor immunity, have also been proven to be associated with WDR72 expression." (PMID 38048211, 2023). "To investigate the mechanism by which WDR72 affects LCSCs, we detected the expression of key molecules of tumor-associated signaling pathways." (PMID 36385964, 2022). "WDR72 depletion suppressed malignant phenotypes in vitro and substantially inhibited tumor growth and metastasis in vivo." (PMID 42224092, 2026). "RT-qPCR validated differential expression of WDR72, ANLN, and SLC16A12 in normal renal versus ccRCC tumor tissues, supporting their potential as diagnostic and therapeutic biomarkers." (PMID 41332473, 2025). "The results revealed ANLN upregulation and SLC16A12 and WDR72 downregulation in ccRCC tumor tissues compared to adjacent normal tissues." (PMID 41332473, 2025). "WDR72 displayed a considerable upregulation at the transcriptional and protein levels within the tumor tissues and showed a correlation with unfavorable prognosis in this study." (PMID 39268080, 2024). "WDR72 expression was related to immune cell infiltration and tumor immune microenvironment in NSCLC." (PMID 37197572, 2023). "Multivariate analysis revealed that tumor size, TNM staging, tumor grade, and metastasis were associated with the expression of WDR72 (p < 0.05)." (PMID 37197572, 2023). "As expected, the WDR72 was found to be expressed at a lower level in tumor sample as a protective gene." (PMID 37740762, 2023). "Analysis results from TCGA showed that the expression of WDR72 was negatively related to Treg cells infiltration which was reported to inhibit tumor immunity and contribute to tumor progression." (PMID 38048211, 2023). "Knocking down of WDR72 was efficient to suppress the growth and metastasis of LCSCs and deterred tumor growth in BALB/c nude mice via regulating the AKT/HIF-1α signaling pathway." (PMID 36385964, 2022). "Innovatively, we developed a prognostic risk model using LASSO and Cox regression on three hub genes (WDR72, ANLN, SLC16A12), integrating multi-omics data for immune microenvironment, tumor mutation burden (TMB), cancer stem cell (CSC) index, and drug sensitivity assessment." (PMID 41332473, 2025). "Our independent IHC experiments further confirmed that the IHC scores of SHH (4.56 ± 1.46 vs. 2.16 ± 0.79, p < 0.0001), EPOP (4.91 ± 1.76 vs. 2.84 ± 1.05, p < 0.0001), and WDR72 (4.73 ± 2.03 vs. 2.91 ± 2.15, p < 0.01) were significantly greater in tumor tissues than in normal tissues." (PMID 41425595, 2025). "Through immune status and tumor microenvironment analysis, our study found that WDR72 may enhance the effect of Nivolumab by suppressing infiltration of Treg cells through regulating fatty acid beta-oxidation." (PMID 38048211, 2023). "Since the hypothesis that methylation of gene promoter may affect tumor prognosis has been confirmed by several literature, we investigated whether the methylation level of WDR72 and PBRM1 genes in promoter affects the prognosis of ccRCC by MethSurv." (PMID 38048211, 2023). "Therefore, we performed immune status and tumor microenvironment analysis to further explore the role of WDR72 in response to ICI based on TCGA database and three clinical trials." (PMID 38048211, 2023). "Previous studies have shown that the functional maturation of Treg cells depends on the synthesis of large amounts of fatty acids, which deeply strengthens our hypothesis that accumulation of Treg cells in tumor microenvironment could be inhibited by WDR72 regulated fatty acid beta-oxidation." (PMID 38048211, 2023). "Therefore, through our analysis, WDR72 may be able to positively regulate fatty acids beta oxidation to inhibit the accumulation of lipid in ccRCC cells and play an anti-tumor role." (PMID 38048211, 2023).
tumor (continued). "The results revealed differential expression of SHH, WDR72, and EPOP between tumor and adjacent normal tissues (P < 0.05), which aligned with our expected findings." (PMID 41425595, 2025). "RT‒qPCR was then conducted to compare mRNA expression levels of WDR72, ANLN, and SLC16A12 in adjacent normal and ccRCC tumor tissues." (PMID 41332473, 2025). "We then conducted a xenograft tumor experiment using the NCI-H716 cell line in nude mice, which demonstrated that WDR72 knockdown significantly suppressed the subcutaneous tumor formation ability of CRC cells." (PMID 39268080, 2024). "For example, some known oncogenes, such as KMT2B and TERT, were dominantly observed in tumor while fusion transcripts with CYP3A5, SERPING1, and WDR72 were only found in normal tissue." (PMID 29212479, 2017). "Finally, immunohistochemistry (IHC) experiments confirmed the differential expression patterns of the SHH, WDR72, and EPOP genes between tumor and normal tissues, corroborating our findings at the mRNA level." (PMID 41425595, 2025). "The difference analysis of 41 paired samples of TCGA-COAD showed that the mRNA levels of ARHGAP4, SIAH2, TRIM45, and WDR72 were significantly upregulated in the tumor group, while MID2 and UBE2D2 showed no statistical difference." (PMID 39268080, 2024). "Finally, we validated WDR72 in human NSCLC; it has a predictive value in NSCLC related to its function in tumor progression and immunity." (PMID 37197572, 2023). "The results revealed that expression levels of SLCO4C1, POU4F1, DNASE1L2, WDR72, LPO, and C7 in tumor tissues were significantly higher than those in normal tissues, while the expression differences of SLC4A4, CELF4, and SLC11A1 were not statistically significant." (PMID 37745305, 2023). "Similarly, we found that WDR72 expression and smoking, tumor size, TNM staging, tumor grade, and metastasis were correlated (p < 0.05)." (PMID 37197572, 2023). "Overexpression of WDR72 decreased the survival and invasiveness of RCC cells, therefore, it may generate tumor suppressive effect in ccRCC." (PMID 38048211, 2023).
cancer (9 papers, 2020 to 2026). A tumor composed of atypical neoplastic, often pleomorphic cells that invade other tissues. "WD repeat-containing protein 72 (WDR72) has been linked to various cancers, but its specific biological function and underlying mechanism in ESCC remain largely unexplored." (PMID 42224092, 2026). "Previous studies on WDR72 were mainly focused on amelogenesis imperfecta (AI), while its role in malignant tumor was rarely reported." (PMID 36385964, 2022). "The TMEM251, AAGAB, ENTR1, SCYL2, and WDR72 were all found to be expressed mainly in cancer cells." (PMID 37740762, 2023). "The function of WDR72 has only been mentioned in a few cancers." (PMID 36385964, 2022). "WDR72 was a cancer suppressor and a potential therapeutic target in RCC." (PMID 33234734, 2020).
kidney disease (1 paper, 2024). "Our results confirm previously identified associations of NEMG (NAT8, GATM, SLC22A2, WDR72, NOS3, AGXT2 and CPS1) with kidney disease and kidney function, providing new information that expands these associations to other kidney disease biomarkers." (PMID 38858654, 2024).
WDR72 also shares sentences with these, for which no sentence is quoted: genetic disease (2 papers); renal tubular acidosis (2); Acidosis (1); esophageal squamous cell carcinoma (1); glioblastoma (1); Hypercalciuria (1); liver failure (1); lymph node metastasis (1); melanoma (1); proliferative diabetic retinopathy (1); Pseudoxanthoma elasticum (1); Renal cyst (1); renal failure (1); rickets (1); type 2 diabetes mellitus (1).